RBP4 (retinol binding protein 4)
Diseases named in the same sentence as RBP4 in open-access papers (continued):
Sharing a sentence is not in itself a finding about the gene and the disease.
diabetic retinopathy (10 papers, 2010 to 2025). "RBP4 has also been implicated in diabetic retinopathy with enhanced expression in cases with proliferative diabetic retinopathy when compared to non–proliferative diabetic retinopathy or no retinopathy." (PMID 20625434, 2010). "The elevated RBP4 plasma levels were linked to diabetic retinopathy and vision-threatening diabetic retinopathy in Chinese T2D patients, suggesting a role for RBP4 in the pathophysiology of diabetic retinopathy problems." (PMID 36911496, 2023). "In a study of diabetic retinopathy, RBP4 levels in patients with diabetic retinopathy were 1.6-fold higher than those in normal participants." (PMID 37510153, 2023). "Higher levels of pro-inflammatory proteins, Reg-3a and RBP-4, might contribute to the pathogenesis of diabetic retinopathy, as the parallel increased concentrations of anti-inflammatory molecules elafin and ZAG might indicate a compensatory mechanism." (PMID 37883447, 2023). "They deduced that RBP4 may play a role in the pathogenesis of diabetic retinopathy and that lowering RBP4 levels may be a novel treatment strategy for diabetic retinopathy." (PMID 33082885, 2020). "In conclusion, we found elevated levels of Reg-3a, RBP-4, elafin and ZAG in advanced stages of diabetic retinopathy." (PMID 37883447, 2023). "In addition we found ALDH1A1, RBP4, APOB, APOA1, RBP1, APOE and RHO genes enriched in retinoid metabolic process as unique GO in diabetic retinopathy." (PMID 28761062, 2017).
liver fibrosis (10 papers, 2016 to 2025). "Consistently, in CHC patients, there was a significant decreasing linear trend of RBP4 dependent on both histological grading and staging progression, and hepatic fibrosis was associated with low RBP4 levels." (PMID 33135589, 2020). "However, RBP4 levels were significantly lower in patients with severe liver fibrosis (n = 42) than in those with no or mild fibrosis (n = 109) (SMD: −1.42; 95% CI: −2.53, −0.30; p = 0.01), suggesting a potential association between RBP4 and liver fibrosis in patients with HCV." (PMID 39589965, 2024). "This nanoparticle system actively recruits plasma proteins, particularly retinol-binding protein 4 (RBP4), which forms a corona on the surface and effectively inhibits collagenase-I expression, thereby ameliorating liver fibrosis." (PMID 37029392, 2023). "Relevant studies have indicated that serum RBP4 concentration is negatively correlated with the severity of disease in early HCV patients, and as the serum RBP4 concentration decreases, the degree of liver fibrosis increases proportionally." (PMID 34889069, 2022). "Researches have found that the concentration of serum RBP4 is negatively correlated with the disease severity in patients with early HCV liver fibrosis, and its concentration decreases as the degree of liver fibrosis increases." (PMID 34889069, 2022). "In moderate/severe NASH, high levels of hepatic RBP4 corelated with lobular inflammation and fibrosis scores, whereas other studies indicate that both serum and hepatic RBP4 levels negatively correlate with the liver fibrosis stage." (PMID 33925827, 2021). "RBP4 was negatively correlated with hepatic fibrosis severity, and with AST and ALT levels." (PMID 39589965, 2024). "This suggests the involvement of RBP4 in liver fibrosis pathogenesis." (PMID 39589965, 2024). "Considering liver fibrosis and liver function are reliable indicators of HCV disease progression, our meta-analysis examined the relationship between RBP4 levels and these factors." (PMID 39589965, 2024). "Among the different adipocytokines (retinol binding protein 4 (RBP4), resistin, apelin, chemerin, vaspin, etc.), adiponectin is one chiefly involved in hepatic fibrosis." (PMID 32718097, 2020). "Interestingly, the expression levels of CXCL13, TNFSF8, and TNFRSF8 correlated negatively with the expression of retinol binding protein 4 (RBP4), which is decreased in cirrhosis, and positively with the expression of COL1A1, which reflects liver fibrosis." (PMID 40014629, 2025). "The positive association of NLR levels and the negative association of FIB-4 scores with RBP4 levels reflected that systemic inflammation (i.e. NLR) is associated with the increase, while hepatic fibrosis is associated with the decrease of RBP4 levels." (PMID 33135589, 2020). "Notably, a significant negative correlation between RBP4 levels and the severity of liver fibrosis, as well as liver function in patients with HCV, was observed." (PMID 39589965, 2024). "The retinol molecules have a high binding affinity with retinol-binding protein 4 (RBP4), and the complex of retinol and RBP4 can play a significant role in directing the NPs to hepatic stellate cells (HSC), which is considerable in the progression of hepatic fibrosis." (PMID 36134930, 2022).
polycystic ovary syndrome (10 papers, 2016 to 2024). A disorder that manifests as multiple cysts on the ovaries. "Compared to healthy women, overweight women with polycystic ovary syndrome (PCOS) have an increased expression of RBP4 in adipose tissue and adipocytes, with a decreased GLUT4 expression." (PMID 39518840, 2024). "Only one study focusing on patients with polycystic ovary syndrome showed that retinol-binding protein 4, which was considered to be highly correlated with serum retinol, was positively related to androgen hormones." (PMID 34869520, 2021). "High RBP4 levels are also observed in the serum of women with polycystic ovary syndrome (PCOS) and in the fluids from swine follicular cysts." (PMID 29558965, 2018). "Serum levels of retinol-binding protein 4 (RBP4), an adipokine thought to affect systemic insulin sensitivity, were compared between women with polycystic ovary syndrome (PCOS) and non-PCOS controls to evaluate the association of RBP4 with clinical, hormonal and metabolic parameters of PCOS." (PMID 31051472, 2019).
psoriasis (10 papers, 2015 to 2025). An autoimmune condition characterized by red, well-delineated plaques with silvery scales that are usually on the extensor surfaces and scalp. "The network pharmacology results revealed that the primary targets of the active ingredients in STT were S100A9, GM2A, REN, MMP12, and RBP4, all of which were primarily associated with psoriasis." (PMID 37653756, 2023). "A beneficial effect has also been observed on retinol-binding protein-4, an adipokine considered as an emerging cardiometabolic risk factor that is increased in patients with moderate-to-severe psoriasis." (PMID 26633680, 2015). "In the imiquimod‐induced murine model of psoriasis, expression of RBP4 in healthy skin is low, increasing only on induction of psoriasis‐like lesions." (PMID 39128883, 2025). "The network pharmacology results revealed that the key targets of active STT components, namely GM2A, REN, MMP12, RBP4, and S100A9, are primarily associated with psoriasis, potentially serving as the basis for the therapeutic effectiveness of STT." (PMID 37653756, 2023). "Beyond skin lesions, psoriasis also affects multiple organs or systems such as cardiovascular diseases or metabolic diseases, in which RBP-4 plays vital roles." (PMID 37711744, 2023). "Recently, increasing studies have found the importance of RBP-4 in multiple diseases, including psoriasis." (PMID 37711744, 2023). "Six-month treatment with adalimumab increased insulin sensitivity and reduced CRP and retinol-binding protein-4 (RBP-4) in a prospective study of 29 patients with moderate-to-severe psoriasis." (PMID 33643281, 2020). "Changes in psoriasis patients of the levels of retinol-binding protein 4 (RBP4), a carrier of retinol (vitamin A); transmembrane protein stimulated by retinoic acid 6 (STRA6); and other retinol metabolic molecules have not yet been fully established." (PMID 31956331, 2020). "The aims of the present study were to create a psoriasis mouse model and to use it to detect the levels of RBP4, STRA6, retinol, and other vitamin A-related molecules in the circulation and in skin lesions." (PMID 31956331, 2020). "Studies have also shown that RBP-4 might be a meaningful factor in psoriasis however, relying on the analysis of a single study have some drawbacks." (PMID 37711744, 2023). "RBP-4 may be a participant in the genesis of psoriasis, and with the application of systemic treatment, the pathway with RBP-4 involved may be blocked." (PMID 37711744, 2023). "Additionally, it would be more beneficial to analyze RBP-4 in psoriasis patients with different comorbidities, especially cardiovascular disease and metabolic diseases." (PMID 37711744, 2023). "Studies have also found a change in RBP-4 levels in psoriasis patients, indicating that RBP-4 may be a meaningful factor in psoriasis." (PMID 37711744, 2023). "RBP4 is believed to be a critical adipocytokine, and the interaction between RBP4 and chronic skin and systemic inflammation in psoriasis could be bidirectional." (PMID 31956331, 2020). "Of note, treatment with acitretin could significantly reduce the plasma levels RBP4 in psoriasis patients, suggesting that RBP4 is a potential target for treatment of psoriasis." (PMID 31521168, 2019). "In our previous work, we hypothesized that RBP-4 might have a protective role in terms of chronic inflammation and comorbidities of psoriasis." (PMID 27864793, 2017). "Meanwhile, considering the higher RBP-4 levels in patients, future studies should pay more attention to the functions of RBP-4 in psoriasis." (PMID 37711744, 2023). "The previous study showed that RBP4 levels were higher in moderate-severe psoriasis patients, and 6-month ADA treatment significantly reduced RBP4 levels, right opposing the results in AS according to our data." (PMID 32210816, 2020). "RBP-4 may be a participant in the mechanism of psoriasis, for the correlation with PASI (psoriasis area and severity index) scores in some research." (PMID 37711744, 2023).
psoriasis (continued). "RBP4, STRA6, and the transformation from retinol to retinoic acid were upregulated, which may be part of the mechanism of psoriasis skin lesion formation." (PMID 31956331, 2020).
Abdominal obesity (9 papers, 2008 to 2024). Excessive fat around the stomach and abdomen. "Some studies have observed the relationship between RBP4 and abdominal obesity and found that serum RBP4 concentrations in humans correlate highly with waist-to-hip circumference ratio, waist circumference, and percent trunk fat." (PMID 25890223, 2015). "In the present study we have observed a positive correlation between RBP4 and waist circumference –a subrogate marker of central obesity- which is in line with previous findings." (PMID 24223837, 2013). "RBP4 could be a marker of abdominal obesity, however, the role of RBP4 in the pathogenesis of NAFLD is not sufficiently elucidated." (PMID 25890223, 2015). "When we further controlled for adipokines, markers of oxidative stress and proinflammatory response, the association of RBP4 with central obesity was abolished but not the association with other MetS components." (PMID 24559154, 2014). "Indeed, RBP4 concentrations were independently related to increased carotid atherosclerosis only in patients with overall and abdominal obesity." (PMID 24651174, 2014). "When we performed the correlation analysis adjusted for age, gender, HOMA and waist circumference as a marker of abdominal obesity, there were significant correlations between the serum RBP4 levels and the serum ALT and GGT levels (r = 0·2004, P = 0·0172; r = 0·3588, P < 0·0001, respectively)." (PMID 17941908, 2008). "Adipocytes release retinol binding protein 4 (RBP4) and visfatin, and their plasma levels are elevated in individuals with abdominal obesity." (PMID 23009606, 2012). "In conclusion, RBP4 could be a marker of abdominal obesity, but the role of RBP4 in the pathogenesis of NAFLD is not sufficiently elucidated." (PMID 25890223, 2015).
acute kidney injury (9 papers, 2008 to 2025). Sudden and sustained deterioration of the kidney function characterized by decreased glomerular filtration rate, increased serum creatinine or oliguria. "Patients with CKD should carefully monitor their intake of preformed vitamin A, because of the risk of pathological accumulation of retinol resulting from elevated levels of serum retinol-binding protein 4 (RBP4) in renal failure." (PMID 34579015, 2021). "RBP4 levels were also correlated with markers of renal failure, specifically sCr (r = 0.224, p = 0.005), but they were not correlated with BNP (r = −0.005, p = 0.958) and ALB (r = 0.199, p = 0.057) levels." (PMID 24099047, 2013). "Accordingly, in all ICU patients, serum RBP4 closely correlated with liver function and increased with renal failure." (PMID 20932285, 2010). "The relative amounts of apo-RBP4 are increased in rats during acute renal failure and RBP4-L and RBP4-LL have been shown to be increased in hemo-dialysis patients." (PMID 18752671, 2008). "As acute renal failure, mainly of prerenal origin during hemodynamic deterioration, is a classical feature of critically ill patients, our study demonstrated a direct correlation between increasing serum RBP4 and decreasing renal function in ICU patients." (PMID 20932285, 2010). "Serum RBP4 concentrations were also correlated with markers of renal failure, specifically increasing creatinine (r = 0.493, P < 0.001), urea (r = 0.389, P < 0.001), cystatin C (r = 0.381, P < 0.001) and decreasing glomerular filtration rate (GFR; r = -0.526, P < 0.001)." (PMID 20932285, 2010). "Because serum RBP4 is also affected by a number of non-metabolic circumstances, such as acute illness, injury, liver and renal failure, respondents with these conditions were precluded from the study." (PMID 24475021, 2014).
heart failure (9 papers, 2020 to 2024). Inability of the heart to pump blood at an adequate rate to meet tissue metabolic requirements. "Consistently, serum levels of both resistin and RBP4 have previously been reported to be associated with LV diastolic dysfunction and development of heart failure, highlighting the importance of these adipokines in the pathogenesis of heart failure." (PMID 36964443, 2023). "So RBP4 is a valuable diagnostic indicator of heart failure, and may be involved in the pathogenesis and development of heart failure." (PMID 35309061, 2022). "The TTR V122I polymorphism described in 3–4% of Black individuals destabilizes the TTR-RBP4 tetramer, thereby displacing RBP4 and promoting amyloid fibril formation that precipitates heart failure and death." (PMID 35995766, 2022). "Retinol-binding protein 4 is involved in the pathological process of heart failure through a variety of mechanisms." (PMID 35309061, 2022). "In addition, it has been reported that circulating retinol-binding protein 4 may be useful in identifying patients with ATTR-CA with V122I mutant heart failure." (PMID 38111336, 2024).
Hyperinsulinemia (9 papers, 2013 to 2024). An increased concentration of insulin in the blood. "It was shown that RBP4 induces inflammatory processes in endothelial cells and promotes hyperinsulinism-induced vascular smooth muscle cell proliferation and migration." (PMID 35334893, 2022). "Collectively, these findings indicate that RBP4 may play an important role in the mediation of signals related to proliferation of VSMCs induced by insulin, which suggests that RBP4 may contribute to vascular remodeling in hyperinsulinemia." (PMID 24604418, 2014).
Nephropathy (9 papers, 2016 to 2026). A nonspecific term referring to disease or damage of the kidneys. "Hence, we performed this study to evaluate the diagnostic value of RBP4 for early kidney damage in T2DM patients." (PMID 38711978, 2024). "However, our initial in vitro studies indicate that RBP4 alone does not adversely affect the sensitivity of cancer cells to anticancer drugs, including those based on platinum or other drugs that lead to kidney damage and may cause an increase in RBP4." (PMID 32156052, 2020). "Rats exposed to either of these halogens also exhibited increased total protein, albumin, and retinol binding protein 4 (RBP4) in the urine indicating significant kidney damage." (PMID 41496587, 2026). "Promising biomarker candidates for kidney damage in Bothrops snakebites were retinol-binding protein (RBP4), beta-2-microglobulin (B2M), cystatin-C (CST3), hepcidin (HAMP), and fatty acid-binding protein (L-FABP)." (PMID 38536893, 2024). "Other authors have also shown that cisplatin increases RBP4 expression in mice by inducing kidney damage." (PMID 32156052, 2020). "A serum level of RBP4 >24.5 ng/mL predicted the presence of nephropathy with 84% sensitivity, 90% specificity, and AUC=0.912 with 86% accuracy; and urinary ACR >37.5 mg/g creatinine predicted the presence of nephropathy with 89% sensitivity, 72% specificity, and AUC=0.819 with 83.3% accuracy." (PMID 38711978, 2024). "Interestingly, elevated plasma RBP4 concentration might be a biomarker of nephropathy and cardiovascular disease in type 2 diabetic subjects." (PMID 30135138, 2018).
pancreatic cancer (9 papers, 2011 to 2025). "For example, a significant elevation in the serum level of RBP4 was found in pancreatic cancer patients, which was significantly decreased after operation than before operation." (PMID 36632438, 2022). "Significant elevation in serum concentrations of LCN2 and RBP4 has been observed in pancreatic cancer patients." (PMID 26131602, 2015). "Also a significant elevation in serum concentrations of RBP-4 and of Serpina1d was found in pancreatic cancer patients." (PMID 32411709, 2020). "Indeed, proteome analysis shows that serum RBP4 is a potential new biomarker of lung and pancreatic cancer." (PMID 23708710, 2013). "Thus, the results of this study show that four serum proteins, apolipoprotein A-IV, vitamin D binding protein, retinol-binding protein 4, and tetranectin are significantly decreased in patients with pancreatic cancer." (PMID 22091389, 2011). "As a result of these validation process, we could confirm that the serum levels of apolipoprotein A-IV, vitamin D-binding protein, plasma retinol-binding protein 4, and tetranectin were significantly decreased in patients with pancreatic cancer." (PMID 22091389, 2011). "Indeed, a recent study showed a highly significant increase of RBP4 level in the pancreatic cancer." (PMID 25250314, 2014). "Of note, the serum level of RBP4 showed no statistically different between patients with pancreatic adenocarcinoma or chronic pancreatitis, indicating it may not be a suitable biomarker for pancreatic cancer." (PMID 36632438, 2022).